SIRT1 (sirtuin 1)
Diseases named in the same sentence as SIRT1 in open-access papers (continued):
Sharing a sentence is not in itself a finding about the gene and the disease.
viral infection (26 papers, 2014 to 2026). "Sirtuin 1 (SIRT1) has been reported to contribute to prevention of viral diseases as well as a chronic infection caused by Mycobacterium bovis." (PMID 36859519, 2023). "A recent study suggested a role for SIRT1 in the susceptibility of older adults to viral infections." (PMID 36139497, 2022). "SIRT1 is the best-characterized, showing powerful deacetylase activity, and it is strongly associated with longevity and diseases caused by virus infection." (PMID 36016356, 2022). "However, most studies on the role of SIRT1 were associated with human disease, and the function of SIRT1 during viral infection in crustaceans was rarely reported." (PMID 36016356, 2022). "However, the potential molecular mechanism underlying the role of SIRT1 during viral infection in crustaceans is poorly understood." (PMID 36016356, 2022). "This study reveals a new mechanism underlying EV71 replication and suggest that SIRT1 could be an agent for the treatment of the viral infection." (PMID 27875274, 2016). "We observed a significant upregulation of SIRT1 protein after Dihydro-R treatment compared to the virus infection group." (PMID 41399758, 2026). "In contrast, SIRT1 deficiency leads to hyperacetylation of IRF3/IRF7, suppressing innate immunity and increasing susceptibility to viral infections." (PMID 40166469, 2025). "Specifically, SIRT1, SIRT2 and SIRT5 have been shown to exhibit potent pro-viral activity by facilitating the replication of a range of viral pathogens, while in certain viral infections, SIRT1, SIRT5, and SIRT6 display anti-viral properties." (PMID 40006932, 2025). "The burgeoning literature increasingly reports on the interaction between sirtuins and viral infections, notably highlighted by the findings that sirtuin 1 (Sirt1) suppresses HBV transcription." (PMID 38239506, 2023). "Another mechanism by which SIRT1 assists viral infection is its recruitment by a virus to the viral genome or replication complex." (PMID 36016356, 2022). "SIRT1 also takes NAD+ as substrate, and some virus infections can induce apoptosis and inflammation by promoting ROS production and reducing SIRT1 expression." (PMID 35746608, 2022). "Over the last decade, much has been learned about the function of SIRT1 in the regulation of host defenses against viral infection." (PMID 36139497, 2022). "Studies in macrophage have shown that NCoR1 depletion leads to increased fatty acid oxidation through derepression of LXR and also increased fatty acid oxidation pathway is known to have a role in limiting virus infection in DCs through Sirt1." (PMID 35849243, 2022). "Upon viral infection, sirtuin 1 (SIRT1) is recruited to deacetylate OTUD3, leading to the inactivation of OTUD3, which relieves MAVS suppression." (PMID 36385557, 2022). "SIRT1 can affect viral replication through its effect on host transcription factors, which can be used in the course of a viral infection." (PMID 34685718, 2021). "SIRT1 action can prevent changes in cell metabolism that accompany some viral infections, including: HSV-1, HCM, HCMV, and keep metabolic homeostasis." (PMID 34685718, 2021). "A recent study reported that the activation of SIRT1 by viral infection further affected STAT1 activation." (PMID 32823491, 2020). "Given that IRES-mediated translation initiation maintains progression of EV71 RNA translation during viral infection, we evaluated the effect of SIRT1 on the regulation of EV71 IRES activity." (PMID 27875274, 2016). "Furthermore, we observed that viral infection induces the expression of SIRT1, which inhibits EV-D68 replication by suppressing 5′-UTR-mediated translation, an effect that is further enhanced by NAD+ supplementation." (PMID 40006932, 2025). "SIRT1 has been associated with prevention of viral diseases, but its role in chronic bacterial infections has not been widely studied." (PMID 36859519, 2023).
viral infection (continued). "Thus, in the following we review what is known about SIRT1 in terms of its regulation of host immune responses during bacterial and viral infections." (PMID 36139497, 2022). "However, several studies have also demonstrated that SIRT1 can be hijacked by viruses to modulate viral or host transcription machineries for the benefit of viral infection, depending on the virus type." (PMID 36016356, 2022). "Besides, this acetylated residue can be removed by sirtuin 1 (SIRT1) upon virus infection, which promptly inactivates OTUD3 and triggers the innate antiviral immune response promptly." (PMID 33511009, 2021). "SIRT1 inhibition has also been proposed in the treatment of virus infections, whereas SIRT2 inhibitors might be useful for the treatment of cancer and neurodegenerative diseases." (PMID 33669990, 2021). "Therefore, the finding concerning the interaction between CqSIRT1 and viral envelope protein may reveal a novel mechanism by which SIRT1 plays a modulatory role during viral infection through targeting of viral structural proteins." (PMID 36016356, 2022). "Moreover, several models have demonstrated relationships between viral infection and SIRT1." (PMID 32823491, 2020). "We have shown that SIRT1 activators attenuate RGC loss during EAE optic neuritis however, neuronal damage in the MHV model of MS occurs by different mechanisms than in EAE, including direct viral infection of neurons and macrophage-mediated myelin stripping of axons." (PMID 24383546, 2014). "SIRT1, a nicotinamide adenine dinucleotide (NAD+)-dependent enzyme, plays a key role in cellular metabolism, but its interaction with NAD+ during viral infections is not well understood." (PMID 40006932, 2025). "Based on these findings, we selected five genes—Nampt, Nmnat2, Sirt1, Sirt2, and CD38—that were consistently upregulated in both RD and A549 cells, to evaluate their protein expression levels after viral infection." (PMID 40006932, 2025). "To further analyze SIRT-1’s role in PV and CVB3 infection, we pretreated H1HeLa cells with EX527 followed by viral infection." (PMID 37850626, 2023). "During viral infection, EV71 stimulates SIRT1 production, sumoylation and a translocation from the nucleus to the cytoplasm, and attenuates the SIRT1 acetylase activity." (PMID 27875274, 2016). "Interestingly, previous studies have reported that the NAD+ synthesis or consumption genes NAMPT, SIRT1, SIRT2, and CD38 were upregulated during various viral infections, while Nmnat2 was found to decrease following Zika virus infection." (PMID 40006932, 2025). "Previously, several studies proved that SIRT1 plays a vital role in various virus infections by binding to viral trans-activator or non-structural proteins with enzymatic activity." (PMID 36016356, 2022). "These 112 products were excluded from downstream pathway analysis because they represent changes because of viral infection and are not specific to SIRT1 silencing." (PMID 26655722, 2016). "Understanding the multifaceted role of SIRT1 in human defense mechanisms against SARS‐CoV‐2 could pave the way for innovative strategies to manage COVID‐19 and similar viral infections, emphasizing the importance of SIRT1 as a potential target for future therapeutic approaches." (PMID 41416347, 2025). "SIRT-1 is important for autophagy initiation, but whether SIRT-1 is essential for the later stages of autophagy (autophagic flux) or translocates to the cytosol during starvation or other stress stimuli, such as viral infection, is unknown." (PMID 37850626, 2023). "In the context of viral infections, in vitro studies have indicated that treatment with a SIRT1 antagonist (EX-527) generates an increase in the production of influenza viruses and human cytomegalovirus (HCMV) infection, while SIRT1 agonists promote a reduction in the production of viral particles." (PMID 34557509, 2021).
viral infection (continued). "Whether the miRNA181a/Sirt1 axis plays a role in TPP1 posttranscriptional regulation and whether TRF2/TIN2/TPP1 fails to recruit telomerase at telomeres during viral infection is under investigation in our laboratory." (PMID 31191531, 2019). "Therefore, the results indicated that inhibition of SIRT1 and SIRT2 is not sufficient to block viral infection but suggested that, instead, inhibition of multiple SIRTs is required to inhibit arboviral infection." (PMID 31289184, 2019). "Our findings suggest that inhibition of at least SIRT1 and SIRT2 is required for antiviral activity, since inhibition of either SIRT and of the combination of the specific SIRT1/2 inhibitors did not block viral infection." (PMID 31289184, 2019).
age (25 papers, 2011 to 2025). A temporal measurement of the time period elapsed since an identifiable point in the life cycle of an organism. "The therapeutic potential of SIRT1 inducers presents a compelling avenue for the treatment of age-related and metabolic diseases." (PMID 40137124, 2025). "SIRT1 is a master metabolic regulator protecting cells from oxidative stress, promoting DNA stability, and decreasing age-related ailments." (PMID 41159029, 2025). "SIRT1, instead, plays a double role.On the one hand SIRT1 serves as age-related cardiac pathological hypertrophyattenuator." (PMID 39077592, 2022). "Circulating miR-34a levels in mice and humans correlated with age-related hearing loss, but SIRT1 did not correlate with human ARHL." (PMID 36204138, 2022). "Therefore, in this study, we evaluated the expression of SIRT1 in the lens epithelium and peripheral blood samples in age-related cataract patients." (PMID 31287252, 2019). "NMN supplementation may represent a novel therapy to restore SIRT1 activity and reverse age‐related arterial dysfunction by decreasing oxidative stress." (PMID 26970090, 2016). "Therefore, we aimed to determine the expression of SIRT1 in age-related cataract patients." (PMID 31287252, 2019). "Therefore, we further concluded that AS and a potentially wide range of other age-related pathologies may exacerbate disease manifestations by inhibiting basal autophagy through suppressing SIRT1 expression with EX-527." (PMID 28881659, 2017). "Because SIRT1 mRNA expression increased significantly with increasing age and was significantly higher in the Pfirrmann grade 3 disc degeneration group, we believe SIRT1 may play a role in aging and age-related chronic disorders." (PMID 22152608, 2011). "A group of young rats was included in the immunoblot to test the known negative effect of age on SIRT1 levels, which has been related to the age-related decline in cognitive functions." (PMID 33375450, 2020).
lymph node metastasis (25 papers, 2013 to 2025). "Nuclear SIRT1 expression was also positively associated with lymph node metastasis (LNM) (p = 0.048)." (PMID 39858444, 2025). "Elevated SIRT1 levels are also associated with higher rates of lymph node metastasis, suggesting its role as a prognostic marker." (PMID 41300302, 2025). "A high expression of SIRT1 was shown to be strongly linked with lymph node metastasis, according to the findings of two studies that were included in this comparative analysis." (PMID 39403142, 2024). "Current studies have reported a high expression of SIRT1 in GC tissues and association with advanced lymph node metastasis." (PMID 37293593, 2023). "SIRT1 overexpression was associated with higher tumor stage, lymph node metastasis, and distant metastasis." (PMID 30930849, 2019). "Elevated SIRT1 level was associated with tumor stage [Relative Risk (RR) = 1.299, 95% CI: 1.114-1.514, P = 0.0008], lymph node metastasis (RR = 1.172, 95% CI: 1.010-1.360, P = 0.0363), and distant metastasis (RR = 1.562, 95% CI: 1.022-2.387, P = 0.0392)." (PMID 30930849, 2019). "Further, we showed that positive SIRT1 expression was significantly associated with lymph node metastasis in AGC patients indicating that SIRT1 expression lead to tumor metastasis that is consistent with the previous report in a cohort of Korean patients." (PMID 28061480, 2017). "High expression of SIRT1 was significantly associated with lymphatic invasion (P = 0.028), vessel invasion (P = 0.016), and lymph node metastasis (P = 0.014) and tended to be associated with more advanced disease stages." (PMID 25146318, 2014). "Moreover, indicators of cancer progression such as tumor differentiation, depth of infiltration, and lymph node metastasis were closely associated with SIRT1 expression." (PMID 41020376, 2025). "However, the higher expression of SIRT1 in the TN type was associated with lymph node metastasis (p = 0.048)." (PMID 39858444, 2025). "In EC, SIRT1 consistently promotes tumor progression, with high SIRT1 expression associated with advanced TNM stage, poor prognosis, lymph node metastasis, and inferior overall survival." (PMID 40567502, 2025). "A clinical study conducted on 344 TNBC patients showed that SIRT1 overexpression correlates with tumor invasion, lymph node metastasis, and shorter disease-free survival." (PMID 41300302, 2025). "High SIRT1 expression is associated with poor prognosis in TNBC, correlating with lymph node metastasis and distant metastatic relapse." (PMID 41436543, 2025). "In a meta-analysis incorporating seven studies, SIRT1 was found to be upregulated more frequently in lymph node metastasis and stages T3/T4 in CRC patients." (PMID 40229278, 2025). "For example, in PAAD, SIRT1 mutations are negatively correlated with overall survival, whereas in BRCA, SIRT1 mutations are associated with increased tumor grade and lymph node metastasis." (PMID 39845948, 2024). "Four studies including 510 cases were enrolled about SIRT1 expression and lymph node metastasis of ESCC." (PMID 35350833, 2022). "The results showed that low expression of SIRT1 was markedly associated with lymph node metastasis (p = 0.023) and negative PR status (p = 0.021)." (PMID 25420528, 2014). "Moreover, decreased SIRT1 was significantly correlated with the tumor clinical stage and lymph node metastasis." (PMID 23805287, 2013). "In addition, the low expression of SIRT1 was associated with lymph node metastasis and negative PR status." (PMID 25420528, 2014). "On the contrary, the overexpression of SIRT1 in hormone receptor-positive patients and HER2+ patients were correlated with lower risks of lymph node metastasis." (PMID 35252011, 2022). "The plasma concentrations of SIRT1 were shown to be lower in individuals with lymph node metastases compared to those without lymph node metastases [(2.67 ± 1.36) ng/mL vs. (3.74 ± 1.19) ng/mL, p = 0.001]." (PMID 41020376, 2025).
lymph node metastasis (continued). "Age, sex, degree of infiltration, and the presence or absence of lymph node metastases in CC patients did not significantly correlate with plasma SIRT1 levels (p > 0.05)." (PMID 41020376, 2025). "The result indicated that SIRT1 expression was lower in ESCC without lymph node metastasis than that with tumor lymph node metastasis (OR = 0.47, 95% CI: 0.31–0.69), and the difference was statistically significant (Z = 3.76, P < 0.05)." (PMID 35350833, 2022). "The results revealed that low expression of SIRT1, lymph node metastasis, and negative PR status were independent prognostic factors of shorter OS and DFS (Model 1)." (PMID 25420528, 2014). "Moreover, there was no discernible relationship between the plasma SIRT1 levels and the existence of lymph node metastases (p > 0.05)." (PMID 41020376, 2025). "SIRT1 could also upregulate matrix metalloproteinase-2 (MMP-2) level in BC cell lines by its deacetylation activity, exhibiting a direct correlation with advanced TNM stage, higher rates of lymph node metastasis (LNM) and poor survival of patients." (PMID 35927590, 2022). "The expression of SIRT1-low/N1IC-high, lymph node metastasis, and negative PR status were also independent prognostic indicators of shorter OS and DFS (Model 2)." (PMID 25420528, 2014).